CTSV (cathepsin V)
Description:
Cysteine protease. May have an important role in corneal physiology.
Synonyms: CATL2; CTSL2; CTSU
Tractability: Small molecule: a structure with a bound ligand is known; a high-quality ligand is known; it belongs to a druggable protein family. Antibody: its Gene Ontology location is reachable by antibodies, with high confidence; UniProt predicts a signal peptide or a membrane-spanning region; the Human Protein Atlas places it where antibodies can reach. PROTAC: a small molecule that binds it is known.
Target class: Cysteine protease; Cysteine protease CA clan; Enzyme; Protease; Cysteine protease C1A family
Chemical probes: RELACATIB (high quality)
Gene: Protein-coding gene on chromosome 9 (97,025,073 to 97,156,556, reverse strand). Ensembl gene ENSG00000136943.
Subcellular location: Lysosome
Subcellular location (Human Protein Atlas): Cytosol; Nucleoli fibrillar center; Nucleoplasm; Plasma membrane
Pathways (Reactome):
Extracellular matrix organization: Activation of Matrix Metalloproteinases; Assembly of collagen fibrils and other multimeric structures; Degradation of the extracellular matrix
Immune System: Endosomal/Vacuolar pathway; MHC class II antigen presentation; Trafficking and processing of endosomal TLR
Gene expression (Transcription): RUNX1 regulates transcription of genes involved in differentiation of keratinocytes
Gene Ontology:
Molecular function: cysteine-type peptidase activity; protein binding; cysteine-type endopeptidase activity; serine-type endopeptidase activity
Biological process: antigen processing and presentation of exogenous peptide antigen via MHC class II; extracellular matrix disassembly; proteolysis
Cellular component: extracellular region; lysosomal lumen; lysosome
Genetic constraint (gnomAD): Loss-of-function variants: 33 observed, 32.1 expected, observed/expected ratio (o/e) 1.03, 90% interval 0.78 to 1.37. The upper end of that interval is the gene's LOEUF score, 1.37, which puts it in group 5 of 6, group 1 being the genes least tolerant of losing a copy. Missense variants: 400 observed, 418.4 expected, observed/expected ratio (o/e) 0.96, 90% interval 0.88 to 1.04. Synonymous variants: 154 observed, 151.91 expected, observed/expected ratio (o/e) 1.01, 90% interval 0.89 to 1.16.
Homologues: Orthologues: chimpanzee CTSV (99% identical), macaque CTSV (87% identical), dog CTSL (81% identical), pig CTSV (81% identical), rabbit CTSV (77% identical), rat Ctsl (75% identical), guinea pig CTSV (70% identical), zebrafish ctsl.1 (53% identical), zebrafish ctss1 (42% identical), zebrafish zgc:110239 (41% identical), Drosophila melanogaster CtsK1 (38% identical), tropical clawed frog ctsl (37% identical), and 34 more. Paralogues in human: CTSL (77% identical), CTSK (50% identical), CTSS (49% identical), CTSH (39% identical), CTSF (33% identical), CTSW (30% identical), CTSC (29% identical), CTSO (28% identical), CTSZ (25% identical), CTSB (24% identical), TINAGL1 (21% identical), TINAG (20% identical).
Diseases named in the same sentence as CTSV in open-access papers:
CTSV is named in the same sentence as 59 diseases in open-access papers, as found by Europe PMC text mining. Sharing a sentence is not in itself a finding about the gene and the disease. The quoted sentences say what the papers report.
breast carcinoma (23 papers, 2010 to 2026). "Using this strict approach, we selected two genes associated with a detrimental prognosis: B3GNT7 and CTSV in BRCA2-mut breast cancers, and three with a favorable prognosis: CD6, CXCL9, and CXCL13 in BRCA1-mut ovarian cancers." (PMID 40647506, 2025). "Cathepsin V (CTSV) is a cysteine protease associated with tumor progression and is correlated with poor prognosis in liver, colon, and breast cancers 21-23." (PMID 39897041, 2025). "We have previously reported that elevated CTSV expression is associated with a poor clinical outcome in ER+ (Luminal A) breast cancer patients." (PMID 38026973, 2023). "More recently, cathepsin V expression has been associated with advancing tumor grade, distant metastasis, and breast cancer recurrence." (PMID 36002710, 2023). "Elevated expression of CTSV is associated with many malignant tumors, such as breast cancer, squamous cell cancer, and colon-rectal cancer." (PMID 38078882, 2023). "Cathepsin V (CTSV) has been shown to be a tumor metastasis-associated protease in colorectal cancer, breast carcinoma and thymic epithelial tumors and is correlated with poor outcomes." (PMID 35494076, 2022). "Studies showed that high expression of CTSV was associated with poor prognosis of breast cancer, and ectopic expression of CTSV increased the number of migrated and invaded colorectal cancer cells in vivo." (PMID 36601599, 2022). "Examination of all breast cancer cases (N = 3951) identified that high CTSV expression was associated with poor prognosis (HR = 1.459, log-rank p = < 0.0001)." (PMID 33298139, 2020). "We report that CTSV expression is associated with poor prognosis in breast cancer, particularly within the ER-positive subtype." (PMID 33298139, 2020). "In relation to breast cancer, previous studies have also shown that CTSV expression is associated with distant metastasis." (PMID 33298139, 2020). "For instance, B3GNT7 and CTSV predicted detrimental prognosis in BRCA2-mut breast cancers, and CD6, CXCL9, and CXCL13 predicted favorable outcomes in BRCA1-mut ovarian cancers." (PMID 40647506, 2025). "Collectively these results suggest that nuclear CTSV is required for histone stability and cell cycle progression in breast cancer cell lines, through regulating the protein expression of the chaperone protein sNASP." (PMID 38026973, 2023). "We then examined the localisation of CTSV in the breast cancer cells in order to understand the relationship between CTSV, histone H3/H4 and sNASP in more detail." (PMID 38026973, 2023). "We recently reported the presence of CTSV in the nucleus of thyroid carcinoma cells and the data presented in this study has now identified that CTSV can translocate to the nuclear compartment of breast carcinoma cells as well." (PMID 38026973, 2023). "In breast cancer, cathepsin V suppresses the expression of GATA3, a member of the zinc finger transcription factor family, by facilitating its turnover via the proteasome." (PMID 36147668, 2022). "CST6, a natural inhibitor of the lysosomal protease CTSV, inhibits bone metastasis of breast cancer by targeting CTSV, suggesting CTSV as a potential target in cancer treatment." (PMID 35443863, 2022). "Among the four key PRGs obtained, cathepsin V (CTSV) promotes the proliferation and invasion of tumour cells in breast cancer and colorectal cancer, but its role in liver cancer is unclear." (PMID 35902905, 2022). "As per our knowledge, CTSV is a type of lysosomal cysteine protease belonging to the peptidase C1 family and is highly upregulated in colorectal and breast carcinomas compared to normal tissues." (PMID 35443863, 2022). "In cancer, high cathepsin V expression was first detected in colorectal and breast carcinomas, and later also in ovarian, endometrial, renal, squamous cell, thymic epithelial, hepatocellular, and thyroid carcinomas." (PMID 36147668, 2022).
breast carcinoma (continued). "Another protein identified in the CAKs medium was cathepsin V – endopeptidase, which elevated expression correlates with several types of cancer, such as colorectal and breast cancer." (PMID 36123693, 2022). "The expression of cathepsin V (CTSV) and human augmin complex unit 3 (Haus3) correlates with the poor prognosis in invasive and ductal carcinoma in situ types of breast cancer and hepatocellular carcinoma, respectively." (PMID 32992741, 2020). "Cathepsin V (CTSV), also known as cathepsin L2, is a lysosomal cysteine peptidase which has an association with poor overall survival of breast cancer." (PMID 32899312, 2020). "The work presented here examines for the first time the relationship between CTSV expression and relapse free survival of breast cancer patients." (PMID 33298139, 2020). "Here we investigate the role of cathepsin V in breast cancer in order to delineate the molecular mechanisms by which this protease contributes to tumourigenesis." (PMID 33298139, 2020). "We have shown that CTSV expression has distinctly different outcomes across breast cancer subtypes, particularly in relation to the ER status of the tumour." (PMID 33298139, 2020). "Collectively, these results suggest that CTSV is localised to the nuclear compartment in breast cancer cells and that targeting CTSV may have potential application to reduce tumour growth by impairing cell cycle progression for ER+ breast cancer." (PMID 38026973, 2023). "Discussion: Collectively these findings support the hypothesis that targeting CTSV may have utility as a novel therapeutic target in ER+ breast cancer by impairing cell cycle progression via manipulating histone stabilisation." (PMID 38026973, 2023). "Cathepsin V upregulation in breast cancer cells compared to normal breast tissue indicates that this protease could be useful for targeted FI." (PMID 36002710, 2023). "Collectively, this work suggested that CTSV may represent an exciting new therapeutic target in ER+ breast cancer, however further work needed to be done to understand the molecular intricacies of CTSV function." (PMID 38026973, 2023). "Expression of cathepsin V has been demonstrated in different molecular subtypes of breast cancer and seems to increase during the transition of ductal carcinoma in situ (DCIS) to invasive breast carcinoma, suggesting this protease contributes to the tumor’s invasiveness." (PMID 36002710, 2023). "Targeting CTSV in tumours such as breast cancers may be of interest as a therapeutic strategy to impair breast cancer cell progression." (PMID 38026973, 2023). "To determine if CTSV may elicit a similar role in breast cancer cells, we examined expression of 4 core histone proteins (H2a, H2b, H3 and H4) as well as linker protein histone H1." (PMID 38026973, 2023). "Whilst these initial breast cancer studies did not clarify the particular subtype within which CTSV expression was elevated, CTSV has previously been associated with ER-positive breast cancers due to its inclusion on the Oncotype DX® genomic test." (PMID 33298139, 2020). "Therefore, to determine whether CTSV may have a similar role in breast cancer cells, we examined the impact of CTSV on cell proliferation using the MCF-7 and ZR75-1 shRNA cell line models, as characterised and reported in our previous publication." (PMID 38026973, 2023). "However, further examination of the paradigm changing localisation of CTSV is critical to understanding the tumour cell intrinsic role of CTSV in breast cancer, which could be exploited for future development of novel therapeutics." (PMID 38026973, 2023). "This would suggest that CTSV may have distinctive roles across breast cancer subtypes; dissecting these roles would require extensive additional research using models representing the different breast cancer subtypes." (PMID 33298139, 2020).
breast carcinoma (continued). "Cathepsin V (CTSV), overexpressed in ER+ breast cancer, promotes tumor cell invasion and proliferation and is associated with poor prognosis." (PMID 41123022, 2026). "By boosting NF-B activity, cathepsin V speeds up the development of bladder cancer and suppresses the production of the GATA3 protein in luminal A breast cancer." (PMID 38078882, 2023). "In contrast, for BRCA2-mut breast cancer, B3GNT7, CTSV, and GSDMC were the most significant." (PMID 40647506, 2025). "Cathepsin V (CTSV/CTSL2) is a cysteine proteinase that can degrade some constituents of the ECM and has been found to be related to the malignancy of tumor cells and the prognosis of patients with breast cancer." (PMID 35557945, 2022). "Our results were also consistent with the prognostic significance of CTSV in HCC and breast cancer." (PMID 35443863, 2022).
colorectal cancer (7 papers, 2021 to 2024). A primary or metastatic malignant neoplasm that affects the colon or rectum. "Few studies have been conducted to investigate the role of the six genes that comprise the 3-GPS (IKBKB-DT, OR7E14P, PLXNA4, LOC401052, RABGAP1, and CTSV) in the context of chemotherapy for colorectal cancer." (PMID 39684481, 2024). "Previous studies have suggested that CTSL is required for cell cycle progression of colorectal cancer cells and glioma cells, with a similar observation made in our examination of CTSV in thyroid carcinoma cells." (PMID 38026973, 2023). "In colorectal cancer cells, cathepsin V function can be regulated by tumor-suppressive tazarotene-induced gene 1, which decreases the stability of cathepsin V and promotes its degradation, resulting in lower cell invasion and migration." (PMID 36147668, 2022). "However, research examining colorectal cancer has identified both CTSL and CTSV in the nuclear compartment, therefore it is plausible that redundancy may exist in certain models." (PMID 38026973, 2023).
breast ductal carcinoma in situ (6 papers, 2020 to 2023). "More recently, CTSV expression was also found to be elevated in breast ductal carcinoma in situ (DCIS), where it is associated with a poor outcome and has potential to predict DCIS progression to invasive disease." (PMID 33298139, 2020). "In addition, CTSV is a potential prognostic biomarker for progression with high CTSV expression shown to be associated with poor outcome in breast ductal carcinomas in situ." (PMID 33810334, 2021). "High expression of cathepsin V in ductal carcinoma in situ correlates with poor prognostic factors (histological grading, hormone receptor negativity, and HER-2 positivity)." (PMID 36797681, 2023).
lung carcinoma (6 papers, 2020 to 2025). "Importantly, we found that the glycosylation band (43 kDa) was positively correlated with lymph node metastasis, which suggests that the glycosylation of CTSV can serve as a risk factor for malignant progression of lung cancer." (PMID 35494076, 2022). "We then analyzed the association of CTSV expression with the prognosis of 73 lung cancer patients." (PMID 35494076, 2022). "Importantly, three bands were observed in most lung cancer tissues but one or two bands were observed in normal tissues; therefore, we suspected that the glycosylation of CTSV might be associated with the progression of lung cancer." (PMID 35494076, 2022). "We treated cancer cells with CTSV antibodies and co-cultured them with PBMCs in light of our obvious findings that CTSV antibodies suppressed lung cancer cell migration and invasion." (PMID 38078882, 2023). "Targeting CTSV with specific antibodies effectively suppressed lung cancer metastasis in a mouse model." (PMID 38078882, 2023). "Patients with metastasized lung cancer have been shown to have an overexpression of the proteolytic enzyme CTSV, which indicates a worse prognosis." (PMID 38078882, 2023). "In the following step, we successfully transfected lung cancer cell lines and stably overexpressed CTSV to varying degrees at the protein and mRNA levels (2 to 4 times greater than usual)." (PMID 38078882, 2023). "CTSV promotes lung cancer metastasis by downregulating adhesion molecules, including fibronectin, E-cadherin, and N-cadherin." (PMID 38078882, 2023). "After that, exploring the molecular mechanisms of how CTSV drives lung cancer tumorigenesis is a promising study." (PMID 38078882, 2023). "We carried out immunofluorescence experiments in CTSV-overexpressing and CTSV knockdown A549 cells to learn more about the role of CTSV in lung cancer." (PMID 38078882, 2023). "We then investigate how lung cancer cells’ abilities for adhesion, migration, and invasion are affected by CTSV inhibition." (PMID 38078882, 2023). "In conclusion, CTSV knockdown inhibited lung cancer’s ability to develop malignantly, and its detrimental effects on cancer metastasis led to its oncogenic activity." (PMID 38078882, 2023). "Our study demonstrates the critical role of CTSV in the immunity and metastasis of lung cancer, suggesting that the CTSV-targeting approach is a promising strategy for lung cancer." (PMID 38078882, 2023). "By cleaving adhesion molecules like fibronectin, E-cadherin, and N-cadherin, CTSV encouraged the spread of lung cancer, which was further supported by protein mass spectrometry and immunoprecipitation analysis." (PMID 38078882, 2023). "In this study, we reported that the overexpression of CTSV in lung cancer patients are positively correlated with poor overall survival." (PMID 35494076, 2022). "Herein, our clinical data, based on RNA-seq, TCGA and GEO datasets, IHC and prognosis analysis, revealed that CTSV is a prognostic biomarker that is upregulated in lung cancer." (PMID 35494076, 2022). "Next, we explored the clinical relevance of CTSV glycosylation in the lymph node metastasis of lung cancer." (PMID 35494076, 2022). "Together, our findings reveal the clinical relevance of CTSV glycosylation and CTSV drives the metastasis of lung cancer, suggesting that the glycosylated CTSV in serum is a promising biomarker for lung cancer." (PMID 35494076, 2022). "Consistently, we showed that glycosylation of CTSV generally exists in lung cancer tissues and lung cancer cell lines, and protein mass spectrometry identified glycosylation at the N221 and N292 residues." (PMID 35494076, 2022). "Western blot analysis of 24 paired lung samples showed that glycosylated CTSV was expressed at different levels in lung cancer tissues." (PMID 35494076, 2022).